TSFM (Ts translation elongation factor, mitochondrial)
Description:
Associates with the EF-Tu.GDP complex and induces the exchange of GDP to GTP. It remains bound to the aminoacyl-tRNA.EF-Tu.GTP complex up to the GTP hydrolysis stage on the ribosome. Participates in mitochondrial translation.
Synonyms: EF-Ts; EF-TsMt; EFTS; EFTSMT
Tractability: PROTAC: ubiquitination databases record sites on it; its protein half-life has been measured.
Gene: Protein-coding gene on chromosome 12 (57,782,731 to 57,808,071, forward strand). Ensembl gene ENSG00000123297.
Subcellular location: Mitochondrion matrix
Subcellular location (Human Protein Atlas): Mitochondria; Nucleoplasm
Pathways (Reactome):
Metabolism of proteins: Mitochondrial translation elongation
Gene Ontology:
Molecular function: protein binding; RNA binding; guanyl-nucleotide exchange factor activity; translation elongation factor activity
Biological process: mitochondrial translational elongation; mitochondrial translation; translational elongation
Cellular component: mitochondrion; mitochondrial matrix
Genetic constraint (gnomAD): Loss-of-function variants: 29 observed, 33.04 expected, observed/expected ratio (o/e) 0.88, 90% interval 0.65 to 1.2. The upper end of that interval is the gene's LOEUF score, 1.2, which puts it in group 5 of 6, group 1 being the genes least tolerant of losing a copy. Missense variants: 394 observed, 398.85 expected, observed/expected ratio (o/e) 0.99, 90% interval 0.91 to 1.07. Synonymous variants: 178 observed, 161.55 expected, observed/expected ratio (o/e) 1.1, 90% interval 0.97 to 1.25.
Gene-disease validity (ClinGen):
ClinGen rates the evidence that TSFM causes each of these diseases.
mitochondrial disease (autosomal recessive): Definitive.
Leigh syndrome (autosomal recessive): Moderate. A progressive neurological disease defined by specific neuropathological features associating brainstem and basal ganglia lesions.
Homologues: Orthologues: chimpanzee TSFM (99% identical), macaque TSFM (95% identical), guinea pig TSFM (89% identical), pig TSFM (88% identical), mouse Tsfm (86% identical), rat Tsfm (83% identical), dog TSFM (82% identical), rabbit TSFM (77% identical), tropical clawed frog tsfm (59% identical), zebrafish tsfm (44% identical), Drosophila melanogaster mEFTs (34% identical), Caenorhabditis elegans tsfm-1 (30% identical).
Diseases named in the same sentence as TSFM in open-access papers:
TSFM is named in the same sentence as 29 diseases in open-access papers, as found by Europe PMC text mining. Sharing a sentence is not in itself a finding about the gene and the disease. The quoted sentences say what the papers report.
hypertrophic cardiomyopathy (3 papers, 2021 to 2022). A condition in which the myocardium is hypertrophied without an obvious cause. "As the respiratory chain function relies on proper mitochondrial gene expression, differential TSFM expression is associated with various diseases such as encephalomyopathy, hypertrophic cardiomyopathy, and MS." (PMID 36405756, 2022). "In terms of cardiomyopathy, variable clinical phenotypes have been correlated with TSFM pathogenic variants, including hypertrophic cardiomyopathy, dilated cardiomyopathy, arrhythmogenic cardiomyopathy with fibro-adipose replacement and biventricular failure." (PMID 35071363, 2021). "In this report, we describe an isolated concentric hypertrophic cardiomyopathy in a 3-year-old proband carrying compound heterozygous variants in TSFM, the c.997C>T [p.(Arg333Trp)] variant and the c.355G>C [p.(Val119Leu)] variant, both in highly conserved regions of the TSFM protein." (PMID 35071363, 2021). "Another homozygous missense mutation was found in the mitochondrial translation elongation factor TSFM gene in a patient with slow progressive childhood ataxia and hypertrophic cardiomyopathy." (PMID 34277617, 2021).
Leigh disease (3 papers, 2019 to 2021). "The collective findings indicate that TSFM mutations are the cause of autosomal recessive mitochondrial cardiomyopathy, encephalopathy with optic and/or peripheral neuropathy, ataxia, and Leigh syndrome." (PMID 34277617, 2021). "Thirdly, as seen in the previously published reports of TSFM variants, phenotypes can range from mitochondrial encephalopathy to optic atrophy, Leigh syndrome, and cardiomyopathy." (PMID 35071363, 2021). "There is evidence that children with hypertrophic or dilated cardiomyopathy who progress slowly due to TSFM mutations develop neurological symptoms that include optic-nerve and/or peripheral neuropathy, ataxia, Leigh disease, and others, which are the main manifestations of the disease." (PMID 34277617, 2021). "Pathogenic Variants in TSFM are known causal for autosomal recessive combined oxidative phosphorylation deficiency type 3 syndrome (COXPD3) [OMIM: 610505] with heterogenous clinical presentation including cardiomyopathy, encephalopathy, leigh disease, ataxia, or combinations of these disorders." (PMID 35071363, 2021).
encephalomyopathy (2 papers, 2021 to 2022). "A next-generation sequencing (NGS)-based multigene panel for mitochondrial dysfunction was used to identify a TSFM homozygous variant, c.547G>A, p.Gly183Ser, associated with early onset encephalomyopathy with sensorineural hearing loss and peculiar neuroimaging features." (PMID 34277617, 2021).
ovarian carcinoma (2 papers, 2022 to 2025). A malignant neoplasm originating from the surface ovarian epithelium. "High expression of TSFM is associated with poor prognosis of ovarian cancer." (PMID 39827178, 2025).
glioma (1 paper, 2021). A benign or malignant brain and spinal cord tumor that arises from glial cells (astrocytes, oligodendrocytes, ependymal cells). "Six of those genes were found in three of the six most enriched ‘glioma TADs’: 2160 (CDK4, TSFM, TSPAN31, B4GALNT1), 2337 (NFATC4) and 2688 (CACNA1G)." (PMID 34341417, 2021).
measles (1 paper, 2023). A highly contagious viral infection caused by the measles virus. "In measles, including six in whole blood (SOAT1, COLGALT2, AC021860.1, HCG11, METTL21B, and MRPL10), six in the lung tissue (GSTM4, PAQR6, RP11-617D20.1, SNX8, METTL21B, and ANKRD27), and two in the transformed fibroblast cells (CBWD2, and TSFM)." (PMID 37020999, 2023).
sarcoidosis (1 paper, 2025). Sarcoidosis is a multisystemic disorder of unknown cause characterized by the formation of immune granulomas in involved organs. "Among them, there were 14 genes (ABT1, BTN2A2, C2orf74, CCDC88B, FAM213A, MDH2, METTL21B, PRSS16, RP3-473L9.4, TCF19, TSFM, UBASH3A, UQCC2, ZSCAN26) associated with sarcoidosis risk consistently across these tissues." (PMID 40075078, 2025). "In addition, our TWAS pinpointed many tissue-specific sarcoidosis-associated genes and found expressions of 14 genes (ABT1, BTN2A2, C2orf74, CCDC88B, FAM213A, MDH2, METTL21B, PRSS16, RP3-473L9.4, TCF19, TSFM, UBASH3A, UQCC2, ZSCAN26) associated with sarcoidosis across all three target tissues." (PMID 40075078, 2025).
mitochondrial disease (4 papers, 2014 to 2025). "Pathogenic variants in any of the four nuclear genes encoding the mitochondrial elongation factors EFG1, EFG2, TUFM, and TSFM have been implicated in causing severe mitochondrial disease." (PMID 39827178, 2025).
tumor (2 papers, 2012 to 2025). "The mitochondrial metabolic pathway regulates mitochondrial ribosomal protein synthesis through MRPL4, MRPL58, and TSFM, enhances mitochondrial oxidative phosphorylation capacity, and provides continuous energy for tumor cells." (PMID 40989695, 2025). "TSFM and MRPL series proteins, as the core of mitochondrial protein synthesis and metabolic regulation, directly affect the functional integrity of mitochondria and tumor metabolic needs." (PMID 40989695, 2025).
TSFM also shares sentences with these, for which no sentence is quoted: multiple sclerosis (3 papers); Ataxia (2); cardiomyopathy (2); colorectal cancer (2); dilated cardiomyopathy (2); infection (2); peripheral neuropathy (2); autosomal recessive disease (1); breast carcinoma (1); coeliac disease (1); glycogen storage diseases (1); invasive ductal carcinoma (1); lobular carcinoma (1); melanoma (1); Mitochondrial encephalopathy (1); neuroblastoma (1); optic atrophy (1); pertussis (1); tuberculosis (1); type 1 diabetes (1).